UGT1A3 (UDP glucuronosyltransferase family 1 member A3)
Description:
[Isoform 1]: UDP-glucuronosyltransferase (UGT) that catalyzes phase II biotransformation reactions in which lipophilic substrates are conjugated with glucuronic acid to increase the metabolite's water solubility, thereby facilitating excretion into either the urine or bile. Essential for the elimination and detoxification of drugs, xenobiotics and endogenous compounds. Catalyzes the glucuronidation of endogenous estrogen hormones such as estradiol and estrone. Contributes to bile acid (BA) detoxification by catalyzing the glucuronidation of BA substrates, which are natural detergents for dietary lipids absorption. Involved in the glucuronidation of calcidiol, which is the major circulating form of vitamin D3, essential for the regulation of calcium and phosphate homeostasis. Involved in the glucuronidation of the phytochemical ferulic acid at the phenolic or the carboxylic acid group. Involved in the glucuronidation of the AGTR1 angiotensin receptor antagonists losartan, candesartan and zolarsartan, which can inhibit the effect of angiotensin II. [Isoform 2]: Lacks UDP-glucuronosyltransferase (UGT) activity but acts as a negative regulator of isoform 1.
Synonyms: UDPGT 1-3; UGT1-03; UGT1.3; UGT-1C; UGT1C; UDPGT; UGT1A3S
Tractability: Small molecule: a high-quality ligand is known. Antibody: UniProt predicts a signal peptide or a membrane-spanning region. PROTAC: its protein half-life has been measured; a small molecule that binds it is known.
Target class: Enzyme; Transferase
Safety:
Unwanted effects reported when the protein is acted on. In parentheses: how it was acted on, where the effect was seen, and who reports it.
adverse reactions (source: ClinPGx)
hand-foot syndrome (source: ClinPGx)
hyperbilirubinemia (source: ClinPGx)
hyperprolactinemia (source: ClinPGx)
liver failure (source: ClinPGx)
nephrolithiasis (source: ClinPGx)
neutropenia (source: ClinPGx)
Gene: Protein-coding gene on chromosome 2 (233,729,042 to 233,773,300, forward strand). Ensembl gene ENSG00000288702.
Subcellular location: Endoplasmic reticulum membrane
Pathways (Reactome):
Drug ADME: Aspirin ADME; Atorvastatin ADME; Prednisone ADME
Metabolism: Glucuronidation
Signal Transduction: NR1H2 & NR1H3 regulate gene expression to control bile acid homeostasis
Gene Ontology:
Molecular function: enzyme binding; glucuronosyltransferase activity; protein homodimerization activity; retinoic acid binding; enzyme inhibitor activity; protein heterodimerization activity; UDP-glycosyltransferase activity
Biological process: bile acid secretion; estrogen metabolic process; flavonoid metabolic process; vitamin D3 metabolic process; xenobiotic metabolic process; cellular response to glucocorticoid stimulus; flavone metabolic process; liver development; retinoic acid metabolic process; monocarboxylic acid metabolic process; steroid metabolic process
Cellular component: endoplasmic reticulum; endoplasmic reticulum membrane
Genetic constraint (gnomAD): Loss-of-function variants: 31 observed, 43.11 expected, observed/expected ratio (o/e) 0.72, 90% interval 0.54 to 0.97. The upper end of that interval is the gene's LOEUF score, 0.97, which puts it in group 4 of 6, group 1 being the genes least tolerant of losing a copy. Missense variants: 737 observed, 697.86 expected, observed/expected ratio (o/e) 1.06, 90% interval 0.99 to 1.12. Synonymous variants: 262 observed, 268.54 expected, observed/expected ratio (o/e) 0.98, 90% interval 0.88 to 1.08.
Homologues: Orthologues: chimpanzee UGT1A3 (98% identical), rabbit UGT1-6 (79% identical), mouse Ugt1a2 (76% identical), mouse Ugt1a5 (75% identical), zebrafish ugt2a7 (40% identical), zebrafish ugt2b5 (39% identical), zebrafish ugt2b1 (39% identical), zebrafish si:ch73-334d15.1 (37% identical), zebrafish ugt5a2 (36% identical), zebrafish ugt5c1 (36% identical), zebrafish ugt5c3 (36% identical), zebrafish ugt5c2 (36% identical), and 97 more. Paralogues in human: UGT1A5 (95% identical), UGT1A4 (93% identical), UGT1A1 (72% identical), UGT1A9 (68% identical), UGT1A8 (68% identical), UGT1A10 (67% identical), UGT1A6 (67% identical), UGT1A7 (67% identical), UGT2B4 (44% identical), UGT2B17 (43% identical), UGT2B15 (43% identical), UGT2B10 (43% identical), and 9 more.
Diseases named in the same sentence as UGT1A3 in open-access papers:
UGT1A3 is named in the same sentence as 29 diseases in open-access papers, as found by Europe PMC text mining. Sharing a sentence is not in itself a finding about the gene and the disease. The quoted sentences say what the papers report.
breast carcinoma (2 papers, 2012 to 2021). "Eltrombopag is a substrate of several drug-metabolizing enzymes, including cytochrome P450 (CYP) 1A2, CYP2C8, uridine diphosphate-glucuronosyltransferase (UGT) 1A1, and UGT1A3, and the agent is also a substrate of breast cancer resistance protein." (PMID 22674141, 2012).
autoimmune hepatitis (1 paper, 2021). Hepatitis caused by autoantibodies. "The study also reports new findings on DMEs profile in autoimmune hepatitis, where only downregulation trend of the studied enzymes was documented (except for UGT1A1 and UGT1A3), but without reaching statistical significance (p > 0.05)." (PMID 34575411, 2021).
beta thalassemia (1 paper, 2021). Beta-thalassemia (BT) is characterized by deficiency (Beta+) or absence (Beta0) of synthesis of the beta globin chains of hemoglobin (Hb). "Additionally, beta-thalassemia patients with the UGT1A3*2 TT genotype had a higher response to deferasirox, as measured by lower liver stiffness values than those with the UGT1A3*2 CC genotype." (PMID 34198586, 2021).
colorectal cancer (1 paper, 2017). A primary or metastatic malignant neoplasm that affects the colon or rectum. "In a study of 1600 colorectal cancer patients and 2500 unaffected siblings, the variation in 4 UGT genes (UGT1A3, UGT1A6, UGT2B4, and UGT2B15) modified risk of colorectal cancer either independently of interactively with nonsteroidal anti-inflammatory use." (PMID 27881391, 2017).
epilepsy (1 paper, 2019). A brain disorder characterized by episodes of abnormally increased neuronal discharge resulting in transient episodes of sensory or motor neurological dysfunction, or psychic dysfunction. "Among the superfamily of UGT enzymes, UGT1 is strongly engaged in the metabolism of drugs used to treat epilepsy (UGT1A4), schizophrenia (UGT1A3 and UGT1A4), hypertension (UGT1A1, UGT1A3, UGT1A7, and UGT1A9), and hypercholesterolemia (UGT1A1 and UGT1A3)." (PMID 30959953, 2019).
Hyperbilirubinemia (1 paper, 2023). An increased amount of bilirubin in the blood. "Haplotype UGT1A1, UGT1A3, UGT1A7 and MDR1 3435 have been associated with hyperbilirubinemia." (PMID 36691090, 2023).
liver dysfunction (1 paper, 2021). "Among the studied UGTs, the most abundant isoenzyme was UGT2B7, and the least one was UGT1A3, irrespectively of the stage of liver dysfunction." (PMID 34575411, 2021).
lung adenocarcinoma (1 paper, 2022). A carcinoma that arises from the lung and is characterized by the presence of malignant glandular epithelial cells. "Our previous study showed that one of the UDP-glucuronosyltransferases (UGTs) family, UGT1A3, is an important prognostic factor for lung adenocarcinoma (LUAD), inhibiting UGT1A3 could significantly improve the efficacy of anti-tumor drugs." (PMID 35155573, 2022).
schizophrenia (1 paper, 2021). A major psychotic disorder characterized by abnormalities in the perception or expression of reality. "We also report the following modules of unknown relevance to schizophrenia: Glucuronidation with FDR= 8.81E−04 (genes UGT1A3 to UGT1A10) and Phase II - Conjugation of compounds with FDR= 5E−03 (SLC35B3, GGT7, MGST3, and UGT1A3 to UGT1A10)." (PMID 33892787, 2021).
cancer (3 papers, 2017 to 2022). A tumor composed of atypical neoplastic, often pleomorphic cells that invade other tissues. "Our previous results demonstrated that UGT1A3 was highly expressed in LUAD and associated with poor prognosis, inhibiting UGT1A3 showed significant anti-cancer effects by enhancing the activity of anti-tumor drugs." (PMID 35155573, 2022). "UGT1A3 plays an important role in intestinal and liver drug metabolism, participating in the metabolism of a variety of cancers, thus promoting the resistance of tumor cells to chemotherapy drugs." (PMID 35155573, 2022).
tumor (3 papers, 2016 to 2022). "While its knockdown lead to inhibition of tumor cells’ proliferation, migration and invasion potentials via downregulation of UGT1A3." (PMID 35155573, 2022). "In our previous study, we indicated that UGT1A3 was an important prognostic factor for LUAD, inhibiting UGT1A3 could significantly improve the efficacy of anti-tumor drugs." (PMID 35155573, 2022). "As UGT1A3 was closely related to tumor drug resistance, discovery of transcriptional relationship between USF1 and UGT1A3 may provide a new idea for the study of drug resistance and therapy, and USF1 could serve as a potential therapeutic target for LUAD." (PMID 35155573, 2022).
UGT1A3 also shares sentences with these, for which no sentence is quoted: alcoholic liver diseases (1 paper); Bladder Cancer (1); cholelithiasis (1); Cirrhosis (1); epileptic seizures (1); hepatitis C (1); Hypercholesterolemia (1); Hypertension (1); infection (1); influenza (1); liver diseases (1); metabolic disease (1); metabolic dysfunction-associated steatotic liver disease (1); neutropenia (1); panic attacks (1); primary biliary cholangitis (1); primary sclerosing cholangitis (1); squamous cell carcinoma (1).